JAK1 (Janus kinase 1)
Diseases named in the same sentence as JAK1 in open-access papers (continued):
Sharing a sentence is not in itself a finding about the gene and the disease.
atopic dermatitis (continued). "Finally, oclacitinib, tofacitinib, and momelotinib (a JAK1/2 inhibitor) all improved allergic dermatitis in a mouse model, including decreasing skin mast cell numbers." (PMID 36230993, 2022). "Alternatively, the modest changes to intracellular cytokine staining pre- and postupadacitinib, despite improvement in atopic dermatitis, could imply that JAK1-mediated allergic immune dysregulation is driven by non–T cells." (PMID 36546480, 2022). "Abrocitinib, a JAK1 selective inhibitor, was approved to treat atopic dermatitis (AD) by the FDA." (PMID 36429017, 2022). "There are four isoforms of JAK: JAK1, JAK2, JAK3 and TYK2, which mediate signaling in pairs specifically associated with particular cytokine and growth factor receptors, most often involved in the pathogenesis of atopic dermatitis." (PMID 36359220, 2022). "Upadacitinib is a selective Janus kinase 1 inhibitor approved for the treatment of several autoimmune and inflammatory diseases, including moderate-to-severe rheumatoid arthritis, psoriatic arthritis, ankylosing spondylitis, atopic dermatitis, and ulcerative colitis." (PMID 39859036, 2025). "Their hypothesis on pathogenesis ranges from the JAK1 mutation and activation of inflammatory STAT-mediated signaling pathways such as the IL-6, TNF-α, or IFN-γ axis to effects such as inflammatory liver infiltration, atopic dermatitis, and eosinophilia." (PMID 37140667, 2023). "Abrocitinib, a selective Janus kinase 1 (JAK1) inhibitor, has demonstrated efficacy in moderate-to-severe atopic dermatitis (AD), although data in patients whose AD is resistant to multiple systemic therapies remain limited." (PMID 42222682, 2026). "Baricitinib is an oral small-molecule inhibitor of JAK1/2 signaling which is approved for the management of RA, juvenile idiopathic arthritis (JIA), atopic dermatitis (AD), AA, and coronavirus disease 2019 (COVID-19)." (PMID 40305472, 2025). "HCIE exerts anti-inflammatory and anti-atopic dermatitis effects in human keratinocytes by modulating the MAPK/NF-κB/NLRP3 inflammasome, JAK1/STAT6 pathway, and skin moisturizing factors." (PMID 40777996, 2025). "Upadacitinib, a reversible janus kinase (JAK) inhibitor targeting the JAK1 enzyme, is FDA-approved for use in individuals over 12 years old for many immunologic diseases, including moderate-to-severe atopic dermatitis." (PMID 40371306, 2025). "Abrocitinib, an oral small-molecule Janus Kinase 1 (JAK1) inhibitor, is primarily approved for treating moderate-to-severe atopic dermatitis (AD) in adults and adolescents aged 12 and older." (PMID 39337910, 2024). "Abrocitinib, an oral small-molecule Janus kinase 1 (JAK1) inhibitor, has been widely accepted for the treatment of moderate-to-severe atopic dermatitis (AD)." (PMID 39300482, 2024). "There is little mechanistic understanding of the pathogenesis of atopic dermatitis (AD) in STAT3 GOF and JAK1 GOF." (PMID 37140667, 2023). "6g is a potent, orally available, pan-JAK inhibitor with IC50 values of 2.8, 2.6, 13, and 58 nM for JAK1, JAK2, JAK3, and Tyk2, respectively, which was approved for the treatment of atopic dermatitis in Japan." (PMID 36770611, 2023). "6b (Baricitinib) is a JAK1 and JAK2 inhibitor developed by Eli Lilly and Company for the treatment of RA, atopic dermatitis, and systemic lupus erythematosus." (PMID 36770611, 2023). "Three JAK inhibitors—ruxolitinib, upadacitnib (JAK1 inhibitor), and abrocitinib (JAK1 inhibitor)—recently gained FDA approval for atopic dermatitis treatment in the U.S." (PMID 36230993, 2022). "JAK1 and JAK2 signaling pathways are involved in dysregulation in atopic dermatitis and asthma immune response and include Th2 response exaggeration, B-cell maturation, and activation of eosinophils." (PMID 34925353, 2021).
atopic dermatitis (continued). "Upadacitinib, a selective Janus kinase 1 (JAK1) inhibitor, has been approved for the treatment of moderate-to-severe atopic dermatitis based on phase 3 randomized trials demonstrating significant clinical improvement in disease severity and pruritus compared with placebo." (PMID 41466898, 2025). "Ruxolitinib 1.5% cream is a selective topical JAK1 and JAK2 inhibitor, which has recently been approved by EMA and MHRA for treating non-segmental vitiligo, while being FDA-approved for both vitiligo and atopic dermatitis." (PMID 40192197, 2025). "In addition, baricitinib, an oral small molecule with potent JAK1 and JAK2 antagonism, has been demonstrated to be effective in reducing the skin lesions and pruritus in atopic dermatitis patients and improving HRQoL)." (PMID 34680614, 2021). "The decreased JAK1 immunostaining after allergen exposure and flare of clinical signs could be explained by the fact that JAK/STAT signaling is inhibited by SOCS proteins, overexpressed in atopic dermatitis." (PMID 37624299, 2023). "Abrocitinib is an oral selective JAK1 inhibitor approved in Europe, the United States and Japan for the treatment of moderate-to-severe atopic dermatitis in adults whose disease is not controlled with other systemic therapies, including biologics, or when the use of such therapies is not indicated." (PMID 36359220, 2022).
psoriasis (53 papers, 2013 to 2026). An autoimmune condition characterized by red, well-delineated plaques with silvery scales that are usually on the extensor surfaces and scalp. "The TYK2/JAK1 signaling cascade is implicated in dendritic cell migration and activation in inflammatory disease processes, such as psoriasis and type 1 diabetes." (PMID 38912581, 2024). "In this study, comprehensive bioinformatics analysis was performed on the expression profiles of tissue samples from patients with psoriasis in the clinical trial of TYK2/JAK1 inhibitor treatment (NCT02310750)." (PMID 40560938, 2025). "For example, upadacitinib, a selective JAK1 inhibitor, achieved complete response in a case series of 4 patients with AD and concomitant psoriasis." (PMID 40535962, 2025). "Background/Objectives: Baricitinib, a selective JAK1/JAK2 inhibitor, shows therapeutic potential in psoriasis; however, its oral use is associated with systemic adverse effects, encouraging the development of topical formulations." (PMID 41599117, 2025). "This dramatic and sustained response highlights the potential role of JAK1 inhibition in modulating complex inflammatory pathways in pediatric psoriasis, particularly in challenging anatomic sites and refractory cases." (PMID 41393061, 2025). "To investigate the role of JAK1, we firstly examined its expression in rosacea and psoriasis patient samples as well as corresponding mouse models." (PMID 40346694, 2025). "These anti‐inflammatory effects align with findings from studies using JAK1–3 inhibitors (e.g., tofacitinib) in chronic inflammatory conditions such as ulcerative colitis and psoriasis, where JAK inhibition reduced inflammation." (PMID 41041963, 2025). "In conclusion, we present a case of a patient with AD who developed psoriasis after initiation of a selective JAK1 inhibitor, abrocitinib." (PMID 40535962, 2025). "In one reported overlap case, a patient with severe psoriasis who developed DM after adalimumab was switched to the JAK1 inhibitor upadacitinib, with significant improvement in both diseases." (PMID 40861474, 2025). "For this purpose, we investigated the effect of tofacitinib (JAK1/3 inhibitor) on disease phenotype improvement in the fibroblast-matrix based AD and psoriasis models." (PMID 38251799, 2024). "This suggests that targeting TYK2 in IL-12/23–driven diseases such as psoriasis is more effective, while additionally avoiding JAK1,2,3 inhibitor hematopoietic safety concerns." (PMID 39403378, 2024). "We report a case of psoriasis-like eruption induced by dupilumab as an adverse effect in a patient with AD, immediately remitted after switching to baricitinib, which inhibits JAK1/2." (PMID 38577056, 2024). "The selective Janus kinase 1 (JAK1) inhibitor abrocitinib has been approved for the treatment of AD and has showed satisfying efficacy and safety in the treatment of psoriasis in clinical trials." (PMID 38633304, 2024). "JAK1/2 inhibitors such as ruxolitinib and baricitinib have shown effectiveness in reducing psoriasis symptoms by modulating the immune response." (PMID 39335596, 2024). "For our studies, we chose tofacitinib (JAK1/3 inhibitor), which is an attractive therapeutic agent for improving the phenotype of psoriasis and AD." (PMID 38251799, 2024). "Regarding JAK inhibitors, the limited specificity and therapeutic index of JAK1, 2, and 3 inhibitors have hindered their use in psoriasis treatment." (PMID 37334353, 2023). "IFN-γ is involved in the pathogenesis of psoriasis by activating JAK1 and STAT1 transcription factors in skin lesions." (PMID 36838711, 2023). "JAK1 polymorphisms were associated with variable risk for EPF and autoimmune thyroid disease, psoriasis, Behçet’s disease, and Vogt–Koyanagi–Harada syndrome." (PMID 35632621, 2022). "Other JAK1/2 inhibitors such as itacitinib, abrocitinib, solcitinib and filgotinib have shown efficacy in phase II trials in psoriasis and psoriatic arthritis." (PMID 35265634, 2022).
psoriasis (continued). "These include the first-in-class inhibitor for JAK 1–3/TYK2 (PF-06263276) in chronic plaque psoriasis (NCT01981681), dual TYK2/JAK1 inhibitor (PF-06673518, pre-clinical) and Tyk2/Jak1 (PF-06700841) for ulcerative colitis, CD, and psoriasis in phase II." (PMID 33802091, 2021). "Its’ inhibitors, including tofacitinib (JAK1/3-inhibitor) and baricitinib (JAK1/2-inhibitor), block the pathway in Th17 cells, which showed promising perspectives in psoriasis treatment." (PMID 33926088, 2021). "It was shown that JAK1 expression correlates with duration of psoriasis and Psoriasis Area and Severity Index (PASI) score." (PMID 34640327, 2021). "More recently, JAK1 expression has been reported to positively correlate with disease duration and Psoriasis Area and Severity Index (PASI) score." (PMID 31649667, 2019). "Next, we measured IL-19 levels in patients with psoriasis in a phase 2 trial (investigating the JAK1/2 inhibitor baricitinib) at baseline and after 12 weeks of treatment with placebo or various doses of baricitinib and compared IL-19 levels with PASI scores." (PMID 30914699, 2019). "In psoriasis patients treated with the JAK1/2 inhibitor baricitinib or the TNFα antagonist etanercept, IL-19 levels were also highly correlated with PASI scores, and decreases correlated with PASI improvement." (PMID 30914699, 2019). "In contrast, psoriasis and LP showed only JAK1 and JAK3 upregulation, while AA and CLE were characterized by a single dermal JAK signal (pJAK3 and pJAK1, respectively)." (PMID 27711196, 2016). "Ruxolitinib, a JAK1/2 inhibitor used in the treatment of hematological diseases, has been tested in topical formulations to treat mild to moderate psoriasis, with favorable results." (PMID 27711196, 2016). "Since the JAK1-STAT pathway plays a critical role in psoriasis and DM, upadacitinib, a highly selective JAK1 inhibitor, may be an effective and safe option for treating refractory concomitant skin autoimmune diseases with JAK1- STAT pathway activation." (PMID 39859462, 2025). "Curcumol may reduce psoriasis-like inflammation via inhibiting JAK1/STAT3 signaling in keratinocytes." (PMID 38914581, 2024). "Patients received treatment with anti-IL-4RA or anti-IL-13 (anti-Th2), anti-IL23 or anti-IL-17A (Anti-Th17), or JAK1 inhibitors (with the ability to target Th1) based on their diagnosis of AD, psoriasis, or LP established by clinical and histopathology criteria." (PMID 39695162, 2024). "JAK1/3 inhibition had a profound effect on normalizing skin morphology as well as expression of markers of skin differentiation, AMPs and proinflammatory cytokines in both psoriasis and AD models." (PMID 38251799, 2024). "JAK1 antagonists were reported to interfere with Th17 polarization in a mouse model of psoriasis." (PMID 26654242, 2015). "However, this treatment may promote immunosuppression; upper respiratory tract and urinary tract infections were among the most common side effects reported in psoriasis patients using JAK1 inhibitors." (PMID 31680865, 2019). "The expression of JAK1 is positively correlated with the PASI score, and JAK1 and STAT3 tissue expression can be used as markers of psoriasis severity." (PMID 39296901, 2024). "CTSB, JAK1, and LTB4R were the only genes found by random forest analysis to be significant indicators of the psoriasis condition in both the whole skin datasets and isolated MCs." (PMID 37681909, 2023). "Ruxolitinib, another JAK1 and JAK2 inhibitor, has been developed as topical cream and studies in psoriasis showed a better efficacy and safety profile compared to vehicle and Non-inferior to calcipotriol-betamethasone combination." (PMID 35265634, 2022). "Baricitinib, an oral highly selective JAK1 and JAK2 inhibitor has also been studied in patients with moderate-to-severe psoriasis in Phase II trials and has shown better efficacy as compared to placebo at doses 8 mg and 10 mg." (PMID 35265634, 2022).
psoriasis (continued). "The JAK1/JAK2/STAT1 and JAK1/TYK2/STAT3 pathways triggered by IFN-γ and IL-22, respectively, are aberrantly activated in psoriasis, as highlighted by the peculiar STAT1 and STAT3 signatures in psoriatic skin lesions." (PMID 30581877, 2018). "Our results indicate that psoriasis is mainly a JAK3 and JAK1 driven disease with a predominance of STAT3 signaling." (PMID 27711196, 2016). "Ruxolitinib, a JAK1 and JAK2 inhibitor, has exclusively been studied as a topical formulation for the treatment of mild-to-moderate psoriasis." (PMID 24883332, 2014). "Phase I and II clinical trials on tofacitinib, a JAK1 and JAK3 inhibitor, reported dose-dependent improvement in patients with psoriasis when compared to the placebo groups." (PMID 24883332, 2014). "Ruxolitinib, a JAK1 and JAK2 inhibitor, has primarily been studied as a topical ointment for mild-to-moderate psoriasis, and it has been compared to other topical therapies, which include topical steroids and topical calcipotriene." (PMID 24883332, 2014). "Tofacitinib, a JAK1 and JAK3 inhibitor, has undergone the most extensive clinical studies of JAK inhibitors in psoriasis treatment." (PMID 24883332, 2014). "Tofacitinib, a JAK1 and JAK3 inhibitor, and ruxolitinib, a JAK1 and JAK2 inhibitor, are the most extensively studied JAK inhibitors in psoriasis." (PMID 24883332, 2014). "Tofacitinib, an oral or topically administered JAK1 and JAK3 inhibitor, and ruxolitinib, a topical JAK1 and JAK2 inhibitor, have been most extensively studied in psoriasis, and both improved clinical symptoms of psoriasis." (PMID 24883332, 2014). "This is a potent JAK1 and JAK2 inhibitor that is currently under investigation for the treatment of psoriasis." (PMID 24170986, 2013). "Together, our data show that curcumol reduces proliferation and inflammatory gene expression in stimulated keratinocytes by inhibiting the JAK1/STAT3 signaling, suggesting that it might serve as a potential therapeutic option for the treatment of psoriasis." (PMID 34314383, 2021). "The combined JAK1/TYK2 inhibitor, SAR-20347, demonstrated in vitro and in vivo concentration-dependent reduction of IL-12, IL-22, and IFNγ-mediated inflammation and tissue pathology in the imiquimod-induced psoriasis model." (PMID 31649667, 2019). "Therefore, the biological functions of these hub genes may be highly consistent during the pathogenesis of psoriasis and TYK2/JAK1 treatment." (PMID 40560938, 2025). "Brepocitinib (formerly known as PF-06700841) is not a selective TYK2 inhibitor (rather a potent TYK2/JAK1 inhibitor), has shown good efficacy in phase II trials in psoriasis with few minor adverse effects, except thrombocytopenia and decreased reticulocyte count." (PMID 35265634, 2022). "In summary, our results show that curcumol reduces proliferation and inflammatory response in keratinocytes stimulated with proinflammatory cytokines by inhibiting the JAK1/STAT3 pathway, suggesting that curcumol might provide a potential therapeutic option for the treatment of psoriasis." (PMID 34314383, 2021). "Our findings are supported by previous siRNA knockdown studies that showed targeted inhibition of JAK1 and TYK2 resulted in an almost complete elimination of IL-17, IL-22, and TGFβ signaling functions that could be harnessed therapeutically to treat patients with psoriasis pathogenesis and cancer." (PMID 29164058, 2017). "Unlike autoimmune diseases like psoriasis or alopecia areata, where only one JAK pathway is dysregulated, AD involves increased signaling through all four JAKs (JAK1, JAK2, JAK3, and TYK2)." (PMID 40151746, 2025). "Some of the hub genes in the pre/post-treatment (TYK2/JAK1) cohort were also identified by GSE14905 and GSE6710 at opposite expression levels as key genes, although GSE14905 and GSE6710 were not included in any pre/post-treatment psoriasis samples." (PMID 40560938, 2025).
psoriasis (continued). "IL‐17 was also not inhibited by JAK1 inhibition as opposed to the pan‐JAK inhibitors, perhaps questioning its efficacy in diseases such as psoriasis and ankylosing spondylitis where both pan‐JAK inhibitors and anti‐IL‐17 biologicals have shown great clinical efficacy." (PMID 37275428, 2023).